AR (androgen receptor)
Diseases named in the same sentence as AR in open-access papers (continued):
Sharing a sentence is not in itself a finding about the gene and the disease.
prostate carcinoma (continued). "Prostate cancer shares many molecular and histologic similarities with luminal cells, including growth dependence on the androgen receptor (AR), as well as AR-dependent expression of seminal fluid proteases PSA and TMPRSS2." (PMID 27536883, 2016). "Studies have shown that the transient activation of AKT by AR is related to cell growth and resistance to apoptosis in prostate cancer cells." (PMID 27340775, 2016). "Our findings indicate that LA has anticancer effects in AR-dependent prostate cancer cells, as revealed by the determination of AR regulation." (PMID 27399684, 2016). "The elevated levels of PHF8 augment AR transcriptional activity and are likely to promote prostate cancer progression at least in part through its ability to promote the AR signaling pathway." (PMID 27991916, 2016). "Although an AR antagonist in combination with a PI3K/AKT pathway blocker curbed castration-resistant prostate cancer in Pten-null mice and human prostate tumor xenografts, a combined regimen of these inhibitors showed low activity in a clinical trial." (PMID 27557496, 2016). "Other important questions remain around Nutlin-3 activity in prostate cancer, including the mechanism of AR downregulation, the relative contribution of cell cycle arrest versus apoptosis, and the impact upon AR-driven pro-survival genes." (PMID 27729622, 2016). "To further verify the interaction we cultured an AR positive prostate cancer cell line (LNCap), and a breast cancer cell line (SKBR3) on the surface of a COP-1 chip, fixed them in PFA, and subjected them to the same analysis." (PMID 27441183, 2016). "We molecularly define transition stages from PIN lesions to hyperplasia/neoplasia and progression to adenocarcinoma by temporal changes in expression of human prostate cancer markers, including the androgen receptor and tumor suppressors, Nkx3.1 and PTEN." (PMID 27634876, 2016). "Flutamide, an androgen receptor antagonist, can increase the expression of DJ-1 in prostate cancer cell lines by increasing DJ-1 protein stabilization." (PMID 27825319, 2016). "AR has emerged as a key molecular determinant in the progression of human prostate cancer and is a preferential treatment for men with metastatic prostate cancer, thus the finding that PC-1 is also associated with prostate cancer progression seems paradoxical." (PMID 27835608, 2016). "All these data suggested that DANCR was down regulated by androgen-AR signaling pathway in prostate cancer." (PMID 27191265, 2016). "Androgen receptor (AR) play a pivotal role in prostate cancer (PCa) development at all stages, including the “androgen-independent” tumors." (PMID 27556357, 2016). "Cells characterized by mesenchymal biomarkers are associated with resistance to radiation, chemotherapeutics and AR-targeted therapies that are commonly used to treat prostate cancer." (PMID 27409172, 2016). "We further investigated molecular mechanisms by which AR inhibits CCL2 secretion in AR-positive human prostate cancer cell lines." (PMID 26701731, 2016). "To date, methylation of the AR promoter region was primarily investigated in relation to prostate cancer, where DNA hypermethylation of the AR promoter region occurs leading to AR downregulation." (PMID 28096796, 2016). "Data from breast and prostatic cancer cell studies indicate that Fgf8 transcription is, in part, under the regulatory control of androgen signaling through androgen receptors (AR)." (PMID 27200347, 2016). "The androgen receptor (AR) pathway plays a central role in prostate cancer (PCa) growth and progression and is a validated therapeutic target." (PMID 26936218, 2016). "Here, we show that down-regulation of AR protein and mRNA can be achieved using TQ with a pronounced impact on androgenic activity in prostate cancer cells." (PMID 26986969, 2016).
prostate carcinoma (continued). "LNCaP abl as well as the parental LNCaP harbor the T878A (formerly T877) AR mutation which lies in the LBD of AR and is the most frequently reported substitution in prostate cancer." (PMID 27486973, 2016). "Androgen receptor (AR) plays a critical role in the development of prostate cancer, and androgen deprivation therapy (ADT) is the first line therapy for most first time diagnostic prostate cancer patients." (PMID 27191265, 2016). "The development of potential cancer chemopreventive and therapeutic agents to suppress AR signaling is highly desirable for clinical treatment on prostate cancer." (PMID 27019751, 2016). "Paradoxically, HDACs are also required for the activation of a fraction of AR target genes of human prostate cancers." (PMID 26862856, 2016). "Depletion of DNAH8 in prostate cancer cells suppressed AR transcriptional activity and proliferation." (PMID 27363033, 2016). "Androgens play a central role in the etiology of prostate cancer, as prostate cancer is dependent on androgen receptor activation for growth and survival." (PMID 27044414, 2016). "Additional studies of KDM3A revealed that its demethylation of H3K9me2/1 facilitates the transcriptional activity of AR, and HIF1α in responding to hypoxia in prostate cancer cells." (PMID 27689328, 2016). "In another study, the treatment of androgen receptor-positive prostate cancer cells with icariside II resulted in downregulation of expression of KLK3 gene, showing the role of icariside II in inhibition of AR signaling." (PMID 27445824, 2016). "Together with the clinical analyses, these results specifically pinpoint a novel role of Snail in regulating AR expression and localization in prostate cancer." (PMID 27409172, 2016). "CCND2 had an inhibitory potential on the proliferation of androgen receptor (AR)-dependent prostate cancer cells." (PMID 27634882, 2016). "The detected ARE recognition by the androgen receptor displays a potential mechanism how SCNAs get translated to a functional, oncogenic level in prostate cancer." (PMID 27623747, 2016). "The data point to a model in which AR+ prostate cancer cells coordinate cell metabolism and signaling to support the demands of oncogenic signaling." (PMID 27248322, 2016). "We also studied the underlying mechanisms contributing to the resistance to androgen-deprivation therapy and poor AR antagonist efficacy in advanced prostate cancer." (PMID 27991915, 2016). "For the treatment of prostate cancer, there are two major ways to target AR signals; surgical/chemical castration and anti-androgens." (PMID 26885620, 2016). "This correlates with a previous report describing clonal dynamics of the AR gene in patients with prostate cancer due to adaption to ADT36." (PMID 27328849, 2016). "For instance, identifying novel TGs of the AR can provide further insight into how the AR drives prostate physiology and prostate cancers become resistant to androgen ablation therapy." (PMID 27723773, 2016). "In this study, we provide evidence that metabolic features of prostate cancer cells can be exploited to sensitize CRPC cells to AR antagonism." (PMID 27248322, 2016). "Combined, these data suggest that LA suppresses cell proliferation and induces apoptosis via the inhibition of AR signaling in androgen-responsive prostate cancer cells." (PMID 27399684, 2016). "The androgen receptor (AR) regulates genes involved in the development and maintenance of the male phenotype, and also plays a role in the growth and survival of prostate cancer (PCa)." (PMID 26936218, 2016). "The AR plays a pivotal role in prostate cancer development and is related to cell cycle progression in the G1/S phase, as well as inhibition of apoptosis." (PMID 27399684, 2016). "N-Methylpretrichodermamide B showed strong cytotoxicity against 22Rv1 human prostate cancer cells resistant to androgen receptor targeted therapies." (PMID 27355960, 2016).
prostate carcinoma (continued). "Yang and co-workers also reported that stromal TGF-β signaling induces AR activation in prostate cancer." (PMID 27863384, 2016). "Recently studies demonstrated that androgen/AR axis participated in CSCs regulation of prostate cancer." (PMID 27167111, 2016). "Another explanation is that even though PC-1 down-regulates AR activity, it still promotes the progression of prostate cancer." (PMID 27835608, 2016). "Development and progression of prostate cancer has been widely associated with the androgen DHT, which activates androgen receptor (AR) signaling to promote prostate epithelial cell proliferation." (PMID 27403764, 2016). "The expression of AR is inhibited by miRNA-18a in prostate cancer, and our analyses show that lower expression of miRNA-18a is linked to better survival prognosis." (PMID 27993167, 2016). "Hierarchical clustering grouped ARBs from all cell lines together, indicating that the AR chromatin-binding profile is very similar in prostate cancer cell models." (PMID 27641228, 2016). "The ACLY-AMPK-AR network can be exploited to sensitize CRPC cells to AR antagonism, suggesting novel therapeutic opportunities for prostate cancer." (PMID 27248322, 2016). "Transcription of AR and AR target genes were then tested in parallel controls in primary epithelial prostate cells (PrECs) and the established prostate cancer cell lines LNCaP, VCaP and 22Rv1." (PMID 27378372, 2016). "The importance of AR signalling is underscored by the clinical utility of castration in producing symptomatic relief and objective responses in men with advanced prostate cancer." (PMID 27120785, 2016). "Nevertheless, our study advances understanding of the prostate cancer genome by identifying the frequency, spectrum and functional impact of widespread AR-GSR events in clinical prostate cancer tissues." (PMID 27897170, 2016). "Four genetically distinct AR-positive and AR-pathway dependent prostate cancer cell lines (CWR-R1, LAPC-4, LNCaP, VCaP) were made resistant to enzalutamide by long-term culture (> 6 months) in enzalutamide." (PMID 27036029, 2016). "The androgen receptor (AR) is a nuclear receptor transcription factor required for normal prostate development and prostate cancer pathogenesis." (PMID 26848868, 2016). "Abnormalities in AR genes are also common in other disorders, such as prostate cancer, hypospadias, cryptorchidism, and infertility." (PMID 26885616, 2016). "EZH2 can also methylate AR in prostate cancer promoting its chromatin binding and the up-regulation of AR downstream targets." (PMID 27793053, 2016). "This suggests that factors in addition to DNAH8 regulate AR-mediated gene expression during prostate cancer initiation and progression, and is consistent with multiple AR regulatory factors being identified in our RNAi screen." (PMID 27363033, 2016). "In LNCaP-104-R1, which are castration-resistant prostate cancer cells that express mutant AR, AR signaling has been suggested to promote ultraviolet or STS-induced apoptosis via BAX protein translocation from the cytoplasm to mitochondria." (PMID 27203692, 2016). "This clinical finding, however, differed from preclinical results that documented inhibition of Pten-null prostate cancer when pharmacologic inhibitors of AR and PI3K/mTORC1 or AKT activity were used concurrently." (PMID 27557496, 2016). "Combining different clinical agents to target multiple pathways in prostate cancer cells, including androgen receptor (AR) signaling, is potentially an effective strategy to improve outcomes for men with metastatic disease." (PMID 26907477, 2016).
prostate carcinoma (continued). "PC-1 was also found to repress AR transcriptional activity in androgen-dependent and androgen-independent prostate cancer cells and attenuate the growth inhibition of AR." (PMID 27835608, 2016). "Our novel finding on dual inhibition of AR and mTORC1 suggests that salinomycin is potentially active as monotherapy against advanced prostate cancer." (PMID 27557496, 2016). "To test if endogenous PHF8 and AR interact with each other, we prepared whole-cell extracts from the AR positive prostate cancer cell line, LNCaP." (PMID 27991916, 2016). "This study elucidated the anticancer mechanism of LA by demonstrating that this effect was mediated via inhibition of AR signaling in androgen-sensitive prostate cancer cells." (PMID 27399684, 2016). "Androgen receptor (AR) is a validated drug target for all stages of prostate cancer including metastatic castration-resistant prostate cancer (CRPC)." (PMID 27576691, 2016). "Because androgen/androgen receptor (AR) signaling promotes prostate cancer progression, standard treatment for patients with advanced prostate cancer employs androgen-deprivation therapy (ADT)." (PMID 26701731, 2016). "Here, we report for the first time the involvement of RON in castrate-resistant prostate cancer and its differential regulation by AR under androgen-proficient and androgen-deprived growth conditions." (PMID 26872377, 2016). "Androgen receptor (AR) is involved in normal prostate development, prostate cancer progression, and response to hormonal-based therapies, such as enzalutamide." (PMID 27409172, 2016). "Circulating androgens like testosterone and dihydrotestosterone (DHT) bind to the androgen receptor on prostate gland and prostate cancer cells, leading to gene transcription." (PMID 26977321, 2016). "This is supported by the importance of the AR in prostate cancer progression and from the outcome of studies using inhibitors of testosterone metabolism to prevent prostate cancer development." (PMID 26986969, 2016). "But AR is a tumor suppressor in the prostate cancer cell line PC3-AR9 in vitro and in vivo, if PC-1 enhance AR transcriptional activity, it should inhibit PC-3-AR9 growth." (PMID 27835608, 2016). "Previous work on AR regulated radiation resistance in prostate cancer suggested a decrease in the activity of PRKDC (or DNAPKcs), a key signalling molecule that initiates early stages of non-homologous end joining, after androgen deprivation." (PMID 27109210, 2016). "Recently, Goodwin and colleagues revealed a positive feedback circuit between DNA-PKcs and the androgen receptor (AR) signal pathway after IR in prostate cancer cells." (PMID 27694690, 2016). "Several studies have shown that down-regulation of the AR results in decreased cell proliferation in androgen-sensitive prostate cancer cells." (PMID 26986969, 2016). "To explore DNAH8 function in prostate cancer and its regulatory effect on the AR pathway, we examined DNAH8 protein expression from eight patient-derived prostate cancer cell lines." (PMID 27363033, 2016). "Liganded receptors have long been successful drug development targets, with selective estrogen and androgen receptor modulators key to the clinical management of hormone receptor-positive breast and prostate cancer for decades." (PMID 27363015, 2016). "In order to accurately tailor the design of microarray studies, the timing and cellular requirements for cell death induced by the combination were determined in AR-dependent prostate cancer cells." (PMID 26907477, 2016). "Since the 1940′s the standard of care for the treatment of advanced prostate cancer has focused on the inhibition of the Androgen Receptor (AR) signaling axis." (PMID 27036029, 2016). "We analysed the interaction of the anti-Androgen Receptor (AR) N-20 antibody, used in the characterization of prostate cancer, with endogenous AR in cancer cells and in FFPE prostate cancer tissue." (PMID 27441183, 2016).
prostate carcinoma (continued). "We have previously demonstrated that ELK1 is necessary for androgen/AR-dependent growth of prostate cancer cells." (PMID 27793987, 2016). "Androgens and androgen receptor (AR) are required by both normal prostate and prostate cancer cells for growth and survival." (PMID 27609145, 2016). "In prostate cancer (PCa) cells the androgen receptor (AR) is recruited by ELK1, via its amino-terminal domain (A/B), as a transcriptional co-activator, without ELK1 hyper-phosphorylation." (PMID 27793987, 2016). "This study provides comprehensive evidence that 11KT and 11KDHT are potent and efficacious AR agonists, capable of driving gene regulation, protein expression and cell growth in androgen-dependent prostate cancer cells." (PMID 27442248, 2016). "Despite the importance of androgen receptor (AR) signalling to prostate cancer development, little is known about how this signalling pathway changes with increasing grade and stage of the disease." (PMID 27120785, 2016). "PC3 is a metastatic human prostate cancer cell line with low AR expression, and was favored in this study to limit interference from non-fluorescent endogenous AR." (PMID 26936218, 2016). "Previous studies have demonstrated that the androgen-responsive pro-survival c-FLIP gene is important in prostate cancer, making it a tractable target to study AR-mediated survival." (PMID 27729622, 2016). "The TMPRSS2:ERG gene fusion is common in androgen receptor (AR) positive prostate cancers, yet its function remains poorly understood." (PMID 27183006, 2016). "Further, dysregulation of AR signaling is thought to be responsible for prostate cancer initiation and progression." (PMID 27203692, 2016). "Several promising targeted-therapeutics for prostate cancer (PCa), primarily affecting the androgen receptor (AR) and the PI3K/AKT/mTOR-pathway, are in various phases of development." (PMID 27783994, 2016). "Ideally, drugs that selectively disrupt the COPI complex and block AR coregulator trafficking would be developed as an effective molecular strategy for attenuating aberrant AR activity in human prostate cancers." (PMID 27365400, 2016). "The pathways enriched in PIN module 160 of the AD sample included prostate cancer/AR signaling pathways and cell cycle/DNA replication pathways." (PMID 27365400, 2016). "In VCaP cells which contain 4- to 5-fold more AR protein than other prostate cancer cell lines, BAY 1024767 was more effective at inhibiting cell proliferation than bicalutamide and enzalutamide." (PMID 26760770, 2016). "N-methylpretrichodermamide B, highly cytotoxic in 22Rv1 human prostate cancer cells, is resistant to androgen receptor-targeted therapies." (PMID 27355960, 2016). "SCD also promotes proliferation and disease progression in prostate cancer by affecting cellular signaling cascades and modulating androgen receptor transactivation." (PMID 27042297, 2016). "This is particularlythe case in prostate cancer, where AR is the driving nuclear receptor andconsequently, substantial parallels exist between AR-mediated prostate cancerdevelopment in men and ER activity in breast cancer in women." (PMID 26884552, 2016). "Surgical or chemical castration targeting the androgen receptor signaling axis has been the mainstay of prostate cancer treatment since the landmark study by Charles Huggins and Clarence Hodges in 1941." (PMID 27036029, 2016). "The development of prostate cancer (PCa) is regulated by the androgen-dependent activity of the androgen receptor (AR)." (PMID 27374083, 2016). "To explore the impact of Snail activation on enzalutamide resistance and AR signaling, we developed a tamoxifen-inducible Snail model in enzalutamide sensitive, LNCaP95 prostate cancer cells." (PMID 27409172, 2016). "Since AR plays an essential role in the onset and progression of prostate cancer, AR degradation leads to mitotic arrest in prostate cancer cells treated with low dose 2-methoxyestradiol (2-ME, an endogenous estrogen metabolite)." (PMID 27007160, 2016).